CRH (corticotropin releasing hormone)
Diseases named in the same sentence as CRH in open-access papers (continued):
Sharing a sentence is not in itself a finding about the gene and the disease.
mental disorder (9 papers, 2013 to 2025). A disease that has its basis in the disruption of mental process. "In summary, our present comprehensive analysis on the stress-dependent recruitment of brain CRH neurons provides starting points for functional characterization brain stress system and for development of new targets to treat stress-related mental disorders." (PMID 37511494, 2023). "In thisreview, attention will be paid to the role of CRH in the regulation of response to stress, as well as to the involvementof extrahypothalamic CRH in pathophysiology and the correction of mental disorders." (PMID 34901719, 2021). "Activation of microglia directly or indirectly by corticotropin-releasing hormone (CRH) could contribute to the pathogenesis of mental disorders." (PMID 26190965, 2015). "Mental disorders, acting as stressors, have the potential to upregulate the HPA axis in TMD patients, leading to the expression and release of corticotropin-releasing hormone (CRH), adrenocorticotropic hormone (ACTH), and cortisol." (PMID 37907704, 2023).
pituitary tumor (9 papers, 2016 to 2025). A benign or malignant neoplasm affecting the pituitary gland. "When the non-pituitary tumor gains the ability to secrete CRH, it stimulates the pituitary gland to produce excessive ACTH." (PMID 41334448, 2025). "Lastly, although extremely rare in the paediatric age range, an extra-pituitary tumour that secretes ACTH or, even more rarely, corticotropin-releasing hormone (CRH), causes ectopic CS." (PMID 40540150, 2025). "It is interesting that tumors exhibiting co-secretion of both CRH and ACTH are occasionally seen in gastroenteropancreatic NENs rather than in pituitary tumors." (PMID 32706866, 2020). "A corticotropin-releasing hormone (CRH) test and inferior petrosal sinus sampling (IPSS) were not performed despite the absence of any displayed pituitary tumor, because it was decided to operate on the meningioma because of its size and localization." (PMID 32423480, 2020).
autism (8 papers, 2012 to 2022). Persistent deficits in social interaction and communication and interaction as well as a markedly restricted repertoire of activity and interest as well as repetitive patterns of behavior. "That the CRH-ACTH system was altered in affected subjects with autism was several times implied (reviewed by Taylor and Corbett)." (PMID 35888093, 2022). "Some studies already suggested an involvement of the corticotropin-releasing hormone (CRH)-adrenocorticotropic hormone (ACTH) system with additional alterations of adrenal gland metabolites in autistic disorders." (PMID 32183287, 2020). "From a more comprehensive standpoint, some studies suggest the involvement of the corticotropin-releasing hormone (CRH)-adrenocorticotropic hormone (ACTH) system with additional alterations of adrenal gland metabolites in autistic disorders." (PMID 32183287, 2020). "From a more comprehensive standpoint, some studies suggest an involvement of the corticotropin-releasing hormone (CRH)-adrenocorticotropic hormone (ACTH) system with additional alterations of adrenal gland metabolites in autistic disorders." (PMID 31075898, 2019). "Because many children with autism have allergic symptoms are more anxious and over-react to stress, we investigated if CRH would affect allergic mast-cell activation." (PMID 22559745, 2012).
corticotropinoma (8 papers, 2013 to 2024). "ACTHomas maintain high ACTH levels as they respond to CRH and AVP, which can be evaluated using the CRH and 1-deamino-8-d-arginine vasopressin (DDAVP) tests, respectively." (PMID 33266265, 2020). "Similarity between corticotropinomas and ectopic ACTH-secreting tumours included their ability to express not only ACTH (or CRH in EAS neoplasms), but also two or more pituitary tropic hormones (GH, PRL, LH, and FSH) and proangiogenic markers (CD31 and VEGF), with equal frequency." (PMID 23509456, 2013). "Immunohistochemical reactions with antibodies against ACTH, PRL, GH, LH, and FSH were performed for comprehensive functional assessment in 46 corticotropinomas and 18 ACTH ectopic tumours (all EAS neoplasms were examined for CRH expression, none of them expressed FSH)." (PMID 23509456, 2013).
Hyperglycemia (8 papers, 2015 to 2025). An increased concentration of glucose in the blood. "Some studies have pointed out that perioperative decreased serum potassium levels are independent risk factors for postoperative delirium, and hypokalemia, along with hyponatremia, low CRH, and hyperglycemia, constitutes a metabolic risk profile for delirium." (PMID 40564453, 2025). "Moreover, corticotrophin-releasing hormone (CRH or CRF) causes hyperglycemia via the hypothalamus-pituitary-adrenal (HPA)-axis." (PMID 25870537, 2015). "The sustained cortisol suppression at 24 h postoperatively correlated with dexmedetomidine's known inhibition of hypothalamic corticotropin-releasing hormone secretion, while attenuated hyperglycemia likely reflects improved insulin sensitivity through reduced catecholamine surge." (PMID 41143178, 2025). "Importantly, these effects are only attenuated following administration of a ganglionic blocker not a CRH antagonist suggesting hyperglycemia associated with HPA axis activation is secondary to central sympathetic activation." (PMID 26064978, 2015). "Resultant elevated NE influences changes in the adrenergic receptors in the hypothalamus, pituitary, and adrenal gland, modulating CRH and ACTH release and acting as a regulatory mechanism to counterbalance the effects of hyperglycemia." (PMID 40650008, 2025). "Direct intracerebroventricular administration of corticotropin-releasing hormone (CRH) in primates is shown to promote sympathoexcitatory effects that lead to an increase in plasma noradrenaline levels, hyperglycemia, and elevations in blood pressure." (PMID 26064978, 2015). "Of interest, CRH-induced hyperglycemia is present even with hypophysectomy or adrenalectomy; thus, this disease model is not due to the HPA axis but to CRH enhancing both epinephrine and NE secretion." (PMID 38927393, 2024).
asthma (7 papers, 2017 to 2023). "Confusingly, however, a murine asthma model showed that CRH deficiency enhances allergen-induced airway inflammation, leading the authors to speculate that inherited or acquired CRH deficiency could increase asthma severity in patients." (PMID 33803422, 2021). "Concurrently, we have addressed importance on mechanism underlying immunomodulatory functions of CRH in ER stress, which might be of great value to prevent subsequent asthma." (PMID 32082160, 2019). "As a defining feature of the stress response, activation of the hypothalamic-pituitary-adrenal (HPA) axis has been demonstrated to be strongly associated with asthma pathogenesis, and corticotropin releasing hormone (CRH) that secreted by the hypothalamus plays a central role in this activation." (PMID 32082160, 2019). "We found CRH was deficient to increase BiP expression while icariin treatment significantly improved the level of BiP both in the fetal hippocampal neurons and the lung tissues of asthma rats in a dose dependent manner." (PMID 32082160, 2019). "Pretreated with LPS and OVA led to an obvious increment of CRH protein expression in the lung (p < 0.001) and CRH cytokine in serum (p < 0.01) of the asthma rats." (PMID 32082160, 2019). "The apparent protection against prematurity afforded by ICS suggests that ICS may have been controlling inflammation and asthma, thereby preventing hypoxia, and consequent CRH release, despite the potential to mimic endogenous corticosteroids." (PMID 33296383, 2020). "However, the UPR signaling component IRE-1α were markedly augmented in the hippocampus of OVALPS-OVA-induced asthma rats as well as in the primary cultured fetal rat hippocampal neurons after CRH stimulation and remarkably decreased in icariin treatment groups." (PMID 32082160, 2019).
diabetes (7 papers, 2018 to 2024). "We also advocate comparative research on antidepressants regarding their impact on metabolism, immunology, the CRH system, diabetes complications, and mortality, considering potential gender differences." (PMID 30885233, 2019).
epilepsy (7 papers, 2017 to 2025). "Taken together, our results suggest that a few neuronal subtypes, particularly the PVALB_RGS5, VIP_CRH, and SST_PENK subtypes, are closely associated with pediatric epilepsy." (PMID 40313715, 2025). "Epilepsy gene group indentified top-ranking signaling pathways that were associated with retinoic acid receptor (6 genes), endothelin-1 (6 genes), Gq alpha protein (5 genes) and corticotropin releasing hormone (5 genes)." (PMID 28904337, 2017). "Three inhibitory neuronal subtypes, PVALB_RGS5, VIP_CRH, and SST_PENK, presented significant transcriptomic alterations related to epilepsy." (PMID 40313715, 2025). "Among the inhibitory neurons, the number of interaction pairs tended to be greater in the epilepsy group than the control group, particularly for the PVALB_RGS5, VIP_CRH, and SST_PENK subtypes, and the VIP_CRH subtype showed the most significant increase." (PMID 40313715, 2025). "A significantly greater strength of interactions between NCAM1-NCAM2 in the astrocyte subtype 4-SST_PENK and between NCAM1-NCAM1 in the astrocyte subtype 4-VIP_CRH in the epilepsy group were observed." (PMID 40313715, 2025). "Among the identified neuronal subtypes, the three inhibitory neuronal subtypes PVALB_RGS5, VIP_CRH, and SST_PENK presented prominent transcriptomic alterations related to epilepsy." (PMID 40313715, 2025). "Targeting the HPA axis—such as by blocking glucocorticoid effects with agents like RU486 or inhibiting CRH signaling with antagonists like antalarmin—is thus being explored as a strategy to improve seizure control while also addressing stress-related psychiatric comorbidities in epilepsy." (PMID 40941042, 2025). "The distinct transcriptomic and functional alterations observed in PVALB_RGS5, VIP_CRH, and SST_PENK subtypes, as well as astrocyte subtype 4, suggest that epilepsy may arise from disruptions in specific subpopulations rather than uniform dysfunction across all cell types." (PMID 40313715, 2025). "In children with known IS etiologies, epilepsy can be controlled by inhibiting the negative feedback regulation produced by excessive corticotropin-releasing hormone secretion in the brain using adrenocorticotropic hormone (ACTH)." (PMID 38041198, 2023). "Contrary to what we hypothesized, we observed a significant decrease in CORT and CRH in PWE with suspected SUDEP compared with either PWE or individuals with no history of epilepsy." (PMID 38914464, 2024).
inflammatory bowel disease (7 papers, 2021 to 2024). A spectrum of small and large bowel inflammatory diseases of unknown etiology. "Several studies have clearly shown that the CRH signaling pathway participates in chronic intestinal disorders, including inflammatory bowel disease (IBD)." (PMID 38546882, 2024). "Also, corticotropin-releasing hormone knockout (CRH-KO) mice have been reported to be used in the study of inflammatory bowel disease and stress." (PMID 36267563, 2022). "Moreover, a recent report indicated that in an IBD mouse model, CRH promotes inflammatory bowel disease by enhancing intestinal macrophage autophagy." (PMID 36552294, 2022). "Inflammatory bowel disease (IBD) and irritable bowel syndrome (IBS) are the most-tested disease models in preclinical studies to ascertain the effectiveness of CRH antagonism." (PMID 36552294, 2022).
breast carcinoma (6 papers, 2007 to 2025). "Evidence for an anti-proliferative effect of CRH in human endometrial adenocarcinoma cells as well as in human and rat mammary cancer cells has been reported." (PMID 17667919, 2007). "After stratification according to the cancer stage, the CH and CRH group patients diagnosed as having stage-II breast cancer demonstrated significantly lower nonfatal MACE risk (IPTW-HR 0.514 and 0.641 respectively) compared with the H group." (PMID 31996695, 2020). "Regarding fatal MACEs, patients with pathological stage-II breast cancer in the CH group had a significantly lower IPTW-HR(0.729, 95% CI: 0.533–0.997); and those in the CRH group patients also had a significantly lower IPTW-HR (0.598, 95% CI: 0.427–0.837)." (PMID 31996695, 2020).
ectopic ACTH syndrome (6 papers, 2014 to 2025). "Longer (48h) dexamethasone suppression tests and dynamic tests with CRH or desmopressin can help to distinguish Cushing’s disease from ectopic ACTH syndrome." (PMID 41283594, 2025). "Ectopic ACTH syndrome or CRH-dependent CS is very rare in children and adolescents." (PMID 25386368, 2014). "Other causes of ACTH-dependent CS include ectopic ACTH and ectopic corticotropin-releasing hormone (CRH) secretion, which are known as ectopic ACTH syndrome (EAS) and ectopic CRH syndrome, respectively." (PMID 32895443, 2020).
Hyponatremia (6 papers, 2014 to 2025). An abnormally decreased sodium concentration in the blood. "Altered levels of TSH and mainly T4 may be evident in laboratory tests, while hyponatremia may present if CRH is elevated." (PMID 38132400, 2023). "Because the endocrinological findings led us to suspect that his hyponatremia and plasma hyposmolality were caused by ACTH deficiency, we performed a acorticotropin-releasing hormone (CRH) test, which showed that his plasma ACTH and cortisol levels did not respond to CRH stimulation." (PMID 24597969, 2014). "Intravenous hydrocortisone or oral prednisone increases cortisol levels, suppressing the CRH and subsequently normalizing ADH secretion, leading to the resolution of hyponatremia." (PMID 37700952, 2023).
iron deficiency (6 papers, 2014 to 2025). "Iron deficiency may also increase the risk of maternal infections, which can stimulate the production of corticotropin-releasing hormone and constitute a significant risk factor for preterm delivery." (PMID 38292987, 2023). "Several mechanisms may underlie this relationship including iron deficiency’s stimulation of corticotropin releasing hormone, which increases fetal cortisol, which in turn inhibits the growth of the fetus." (PMID 25195204, 2014).
panic disorder (6 papers, 2012 to 2024). An anxiety disorder characterized by multiple unexpected panic attacks with persistent concern of recurring attacks. "Smoller and colleagues performed one of the first genetic association studies of CRH by studying children from families in which the parents were diagnosed with panic disorders." (PMID 23077729, 2012). "Introduction of interoceptive stress by means of the dexamethasone-corticotropin-releasing-hormone (DEX-CRH) test into the TSST paradigm provoked a less pronounced decrease in HRV in patients with panic disorder as compared with healthy controls." (PMID 36417141, 2022).
Abdominal obesity (5 papers, 2014 to 2024). Excessive fat around the stomach and abdomen. "Similarly, cortisol responses to ACTH and CRH were higher in obese women with abdominal obesity than in women with peripheral fat distribution." (PMID 24535466, 2014). "The prolonged activation of the HPA axis with the attenuation of negative feedback in the HPA axis, which inhibits CRH and stimulates NPY expression, can be associated with abdominal obesity." (PMID 30717384, 2019).
adrenal adenoma (5 papers, 2014 to 2025). "We present the first documented case of adrenocorticotropic hormone (ACTH)-dependent CS resulting from CRH secretion by an adrenal cortical adenoma." (PMID 40927294, 2025). "Serum ACTH concentrations are not suppressed in about half of pregnant women with cortisol-secreting adrenal adenoma due to placental CRH." (PMID 25544906, 2014). "We present a unique case of CS due to ectopic CRH production from an adrenal adenoma." (PMID 40927294, 2025). "We present a unique case of CS resulting from ectopic CRH secretion from an adrenal adenoma." (PMID 40927294, 2025). "This case highlights the importance of considering ectopic CRH secretion in the differential diagnosis of atypical ACTH-dependent CS, especially in patients presenting with adrenal adenomas." (PMID 40927294, 2025). "Histopathological analysis confirmed an adrenal cortical adenoma showing focal immunoreactivity for CRH and absence of ACTH expression." (PMID 40927294, 2025). "However, to our knowledge, the ectopic CRH production by an adrenal adenoma has not previously been reported in the literature." (PMID 40927294, 2025).
adrenal crisis (5 papers, 2018 to 2024). "Two Dutch patients did allow to be retested, although they used daily hydrocortisone (1 based on a CRH test and the other after an event during surgery, which at that time was misinterpreted as an adrenal crisis)." (PMID 32232324, 2020). "Additionally, in adrenal crisis, there is no inhibition of corticotropin-releasing hormone (CRH) secretion, which further suppresses the appetite." (PMID 37510716, 2023). "If CRH and ACTH are suppressed, then discontinuation of prednisone may result in adrenal insufficiency and in times of physiologic stress may precipitate a life-threatening adrenal crisis (acute adrenal insufficiency)." (PMID 30131926, 2018).
dementia (5 papers, 2023 to 2024). Loss of intellectual abilities interfering with an individual's social and occupational functions. "Reduced HGF/MET signaling contributes to synaptic pathology in the 5 × FAD mouse model of AD; while FGF2 gene transfer restores hippocampal functions in APP/PS1 mice; CRH (corticotropin-releasing hormone) has been proposed to play important roles in AD and other dementias." (PMID 39234102, 2024).
fetal growth restriction (5 papers, 2014 to 2022). A fetus that does not grow beyond the 10th percentile of conventionally accepted weight for gestational age. "High levels of corticotropin-releasing hormone had been observed in relation to fetal growth restriction and birth defects." (PMID 30679633, 2019). "In humans, elevated third trimester placental CRH concentrations have been associated with increased risks of spontaneous PTB and/or fetal growth restriction." (PMID 26276498, 2015). "Placental CRH concentration is a significant predictor of spontaneous preterm birth and intrauterine growth restriction (IUGR), and can influence hippocampal development in the fetus." (PMID 24574961, 2014). "The treatment of BeWo cells with exogenous CRH results in the elevation of cellular corticotropin releasing hormone receptor 1 (CRHR1) levels, which are significantly reduced in PE and intrauterine growth restriction (IUGR)." (PMID 36187484, 2022). "Higher levels of CRH may represent one possible biologic pathway linking PFAS and stress exposures to preterm birth, shortened gestational length, fetal growth restriction, and early childhood neurodevelopment." (PMID 33824413, 2022).